RN7SKP117 (RN7SK pseudogene 117)
Gene: Miscellaneous RNA gene on chromosome 5 (125,350,868 to 125,351,131, reverse strand). Ensembl gene ENSG00000222107.
Homologues: Orthologues: chimpanzee 7SK (96% identical), mouse Gm56077 (77% identical). Paralogues in human: RN7SKP189 (81% identical), RN7SKP9 (80% identical), 7SK (80% identical), RN7SKP217 (80% identical), RN7SKP133 (79% identical), RN7SKP176 (79% identical), RN7SKP80 (79% identical), RN7SKP102 (78% identical), RN7SKP131 (78% identical), RN7SKP250 (78% identical), RN7SKP255 (78% identical), RN7SKP47 (78% identical), and 283 more.